CCL5 (C-C motif chemokine ligand 5)
Diseases named in the same sentence as CCL5 in open-access papers (continued):
Sharing a sentence is not in itself a finding about the gene and the disease.
tumor (continued). "As the expression of Ccl5 was mostly reduced (about 5‐folds) in HIF‐1α KO fibroblasts and up‐regulated (about 2.5‐folds) in HIF‐1α MOCK fibroblasts treated with hypoxia, we speculated that CCL5 might play important roles in the promotion of tumour cell growth." (PMID 33943003, 2021). "CCL5 knockdown reduced tumor migration and invasiveness in both the cell lines, and therefore targeting the CCL5/CCR5 axis might act as a novel therapeutic strategy for EC." (PMID 33390169, 2021). "We hypothesized that tumor CCL5 expression regulates macrophage reprogramming through an indirect mechanism." (PMID 34298673, 2021). "However, it has also been shown that Tregs generally express higher levels of CCR5 compared to effector T cells and that tumor-derived CCL5 promoted an influx of Tregs, which resulted in increased tumor growth." (PMID 34203869, 2021). "Similarly, cells treated with BJJP had higher expression of CCL5 mRNA, which was consistent with increased levels of CCL5 protein in human tumor cells." (PMID 34899325, 2021). "Furthermore, we show that macrophage education occurs through an indirect mechanism involving stimulation of tumor cells by CCL5." (PMID 34298673, 2021). "Both subsets of CD8+ T cells from tumor samples expressed higher effector genes than nonmalignant samples, including chemokines (e.g., CCL5), cytotoxicity-associated genes (PRF1, GZMA, GZMB, GZMH), and proinflammatory cytokines (e.g., IL-32)." (PMID 34921160, 2021). "It was also found that tumour-derived osteopontin induces the production of CCL5 by the MSCs." (PMID 35006432, 2021). "The secretion of CCL5 from HIF‐1α high expressed fibroblasts might be combined with CCR5 to promote the growth of tumour cells." (PMID 33943003, 2021). "Analysis of The Cancer Genome Atlas (TCGA) transcriptome data confirmed that multiple chemokines are associated with immune cell infiltration in human tumors, and revealed C-C Motif Chemokine Ligand 5 (CCL5) as the chemokine most highly correlated with immune infiltration across several tumor types." (PMID 34030676, 2021). "Interestingly, CCL7, CCL19, CXCL7, NRG3, SLPI, OPN, and HGF in macrophages are upregulated in response to increased tumor CCL5 expression." (PMID 34298673, 2021). "However, direct stimulation of tumor cells with CCL5 led to an increased macrophages capable of driving tumor cell invasion." (PMID 34298673, 2021). "However, treatment with recombinant human CCL2 (rCCL2) or CCL5 (rCCL5) reversed TAM migration decreased by ILT4-downregulated tumor cells." (PMID 33537094, 2021). "Moreover, circIGF2BP3-mediated CCL5 downregulation in the tumor region was blocked following PKP3 silencing." (PMID 34416901, 2021). "In tumour microenvironment, CCL5 is involved in many immune responses in TME." (PMID 33943003, 2021). "One approach to mimic the inflammatory niche is to generate TNF-α-primed-hBMMSCs that secrete high levels of CCL5, which is involved in the CRC-related CCl5/CCR1/β-catenin/Slug signaling pathway that promotes tumor cell proliferation, EMT, migration, and invasion." (PMID 33849537, 2021). "CCL5 concentration correlated negatively with day 21 tumor size (Spearman, r = −0.771, p < 0.0001)." (PMID 34064933, 2021). "Importantly, mRNA levels of Ccr2 and Ccr5, known to be differentially expressed by TAM1 and MDSCs, were enhanced in isolated control tumours compared to liver tissues, postulating an enhanced presence of Ccl2 and Ccl5-responding myeloid cells." (PMID 34830835, 2021). "Moreover, pro-inflammatory cytokines (IFN-γ, TNF-α) and chemokines (CCL3, CCL4, and CCL5) secreted by NK cells stimulate other lymphocyte populations in the tumor microenvironment or exert a direct anti-tumor effect." (PMID 34203935, 2021). "Consequently, elevated PD-L1 expression as well as T-cell recruitment by proinflammatory cytokine CXCL10 and CCL5 occur in the tumor microenvironment." (PMID 34630387, 2021).
tumor (continued). "In addition to CXCL10, the injection of anti-IFN-γ also significantly impaired the production of CXCL9 and CCL5 in the tumour microenvironment compared to isotype antibody-treated tumours." (PMID 33925140, 2021). "Additionally, correlation analysis of IHC scores demonstrated that CCL5 expression was markedly correlated with p-NF-κB expression in xenograft tumor stroma." (PMID 34108603, 2021). "Therefore, it is plausible that alcohol can reduce the number of tumor-toxic CD8+ T cells via CCL5 upregulation, a process that would be anticipated to contribute to colorectal carcinogenesis." (PMID 34503214, 2021). "Further studies are required to validate CCL5 as a tumour marker in LAPC." (PMID 33100327, 2021). "Reduced CCL5 expression leads to desertification of tumor-infiltrating lymphocytes." (PMID 34218795, 2021). "The results revealed that treatment with BJJP increased CCL5 levels in tumor cells." (PMID 34899325, 2021). "Moreover, tumor areas with high levels of CD146+ pericytes showed intense CCL5 staining whereas the areas with sparse CD146+ pericytes showed scarce CCL5 staining." (PMID 34239070, 2021). "In conclusion, these findings suggest that the METTL14/CCL5/Tregs axis is a potential signaling pathway for regulating tumor immunity, and might become novel therapeutic targets for ccRCC." (PMID 34122497, 2021). "Considering that CCL5 is known as a chemoattractant for macrophages, CCL5 might promote tumor progression partly by recruiting macrophages to the tumor area." (PMID 33671956, 2021). "Together, IL-6 and CCL5 are key enhancers of TNBC tumor growth and metastasis." (PMID 34445170, 2021). "In breast carcinoma, CCL5 is secreted by tumor-residing MSCs." (PMID 33472580, 2021). "By analogy with Tie2/HSV-TK-MSCs, after injection of these cells in the HCC mice model, CCL5/HSV-TK-MSC had more achievements in HCC tumor eradication, revealing that application of different promoter sequence is important in the anti-cancer effect of this strategy." (PMID 34249257, 2021). "In conclusion, molecules and growth factors released by activated platelets (EGF, PDGF, TGF-β, IGF and CCL5) may protect tumor cells from chemotherapy by promoting the expansion of ALDH+ and CD133+ OvCa-CSCs, favoring drug resistance and tumor relapse." (PMID 33809553, 2021). "Furthermore, RNA sequencing comparing EGFRi treatment and baseline tumor showed that two genes, chemokine (C-C motif) ligand 5 (CCL5) and FYB, were significantly downregulated." (PMID 34204797, 2021). "Importantly, CCL5 has been reported to alter the functionality of TAMs toward a tumor-promoting phenotype in colorectal cancer." (PMID 33968034, 2021). "Moreover, the intraepithelial tumor-infiltrating lymphocytes recruited by tumor chemokine CCL5 release IFN-γ to activate TAMs and DCs to secrete CXCL9, which in turn establishes a positive loop effectively amplifying T cell recruitment in EOC." (PMID 34248988, 2021). "Moreover, anti-ILT4 or anti-PD-L1 treatment markedly decreased the expression and secretion of CCL2 and CCL5 in both tumor cell lines with a synergistic effect in the combination treatment group." (PMID 33537094, 2021). "Treatment with Met-CCL5 decelerated tumor growth and macrophage infiltration." (PMID 34503058, 2021). "Finally, we examined the importance of tumor-derived FGF-5 to CCL5 expression in mammary fibroblasts." (PMID 33868996, 2021). "An in vitro evaluation of a clinical trial for oncolytic virotherapy with 12 patients revealed that receptor/ligand pairs C-X-C motif chemokine receptor-1 (CXCR1)/IL-8 and CC chemokine receptor 1/CC chemokine ligand 5 (CCR1/CCL5) were involved in successful migration of MSCs to the tumor." (PMID 33287630, 2021). "The secretion of CCL5 mainly comes from T lymphocytes, macrophages, platelets, fibroblasts and several types of tumour cells, which is not only related to the immune response against tumours, but also to the cancer progression and metastasis." (PMID 33943003, 2021).
tumor (continued). "cDC1 express XCR1, as well as CCR1 and CCR5, both of which bind CCL5 and have antitumor functions; they can attract and activate tumor-specific CD8 T cells, and internalize and transport tumor antigens to lymph nodes, where they may cross-prime CD8 T cells." (PMID 34936871, 2021). "Here we show that the RKIP-mediated inhibition of CCL5 expression and F4/80+ cells tumor infiltration can be reversed by silencing of of RhoA expression suggesting RKIP may regulate CCL5 expression through RhoA GTPases." (PMID 34465801, 2021). "CTCs gradually upregulated the CCL5 expression during their transit from the tumor efferent vessel to peripheral vessels, which led us to consider whether the peripheral Tregs could be the extrinsic factor inducing CCL5 expression in CTCs." (PMID 34215748, 2021). "One type of oncolytic virus has been utilized to convey the chemokine CCL5 to the tumor cells." (PMID 33494834, 2021). "We first tested how increased tumor CCL5 expression regulated tumor EV secretion." (PMID 34298673, 2021). "When we generated a CCL5 knockdown H22 cell line and implant to tumor bearing mice, the tumor weight in shRNA CCL5-Ctrl mice was higher than shRNA Ctrl-Ctrl, which suggested CCL5 may have an anti-tumor effect." (PMID 34899325, 2021). "Given its chemotactic properties, we hypothesized that intratumoral delivery of recombinant CCL5 protein may enhance immune cell recruitment and control tumor growth." (PMID 34030676, 2021). "The majority of studies claim a tumour-promoting role for CCL5." (PMID 34638423, 2021). "However, in HCC with CTNNB1 gene mutations, the recruitment of pro-inflammatory dendritic cells and, therefore, T cells to the tumor is abrogated by suppressing the production of chemokines CCL4 or CCL5 by tumor cells." (PMID 34632251, 2021). "Moreover, HIF‐1α‐expressed CAFs secreted CCL5 by activating NF‐κB signalling pathway, thus promoting the tumour growth of LC." (PMID 33943003, 2021). "Moreover, neutralizing CCL5 partly reversed PARPi-induced fibroblast activation and boosted the tumor inhibitory effect of PARPis in both BRCA1/2-mutant and BRCA1/2-wild type xenograft models." (PMID 34108603, 2021). "Upon secreting CCL5, tumour cells recruit CCR5-expressing TAMs." (PMID 34638423, 2021). "This shows that targeted recovery of RKIP expression to reduce the secretion of CCL5 in tumor cells might be an important strategy to reduce macrophage infiltration." (PMID 34683963, 2021). "The CCL5/CCR5 pathway also supports tumour cell invasion by activating downstream pathways such as PI3K/AKT and calcium/calmodulin-dependent protein kinase II (CaMKII) that ultimately result in the production of matrix metalloproteinase-2 (MMP-2) and -9 (MMP-9)." (PMID 33803414, 2021). "As chemokines, CCL8 and CCL5 are involved in tumor cell proliferation and metastasis." (PMID 34307121, 2021). "This study reported that patients with low CCL5 and TILs had an increased residual tumor size." (PMID 34988021, 2021). "EBV-infected NPC cells showed increases CCL5 expression and enhanced tumor angiogenesis." (PMID 34204797, 2021). "Notably, the overexpression of tumour-derived CCL5 and myeloid cell-secreted CXCR3 ligands are crucial in manipulating CD8+ T cell infiltration in solid tumours." (PMID 34527583, 2021). "CCL5 serves as chemoattractant for lymphocytes and promotes tumor-supportive TH2 polarization." (PMID 34768877, 2021). "Furthermore, PBRM1MUT ccRCC tumors recruit significantly higher numbers of mast cells into the tumor microenvironment, and CCL5 was upregulated in siPBRM1 cells, suggesting that mast cells were recruited by CCL5." (PMID 33177244, 2020). "CCL5 stimulated tumor growth and invasiveness and promoted immunosuppressive M2-TAM polarization." (PMID 32630699, 2020). "Tumor-infiltrating DCs secretes a large amount of CCL5 in human colon cancer specimens." (PMID 33148302, 2020).
tumor (continued). "M-MDSC and inflammatory monocytes are recruited to tumours through a CCL1, CCL2, and CCL5-induced chemokine cascade that is propagated by cancer cells and has been found to be retained within primary tumours by CCL3 produced via CCR-2 activated mechanism in metastasis-associated macrophages." (PMID 32121014, 2020). "Here, miR‐3473b inhibitor significantly reduced the exosome‐mediated inflammatory genes including Il6, Ccl1, Ccl2, Ccl5 and Cxcl2 expression in fibroblasts, which suggest the potential role of exosomal miR‐3473b in establishing tumour‐promoting inflammation environment." (PMID 32449597, 2020). "High levels of CCL5 decreased the time between tumor treatment and recurrence." (PMID 32630699, 2020). "TAK-779 inhibits both CCL5-induced proliferation and invasion of tumor cells." (PMID 32630699, 2020). "However, CCL5 is a double-edged sword in cancer, because it also promotes antitumor immunity by recruiting anti-tumor T cells and dendritic cells to the TME, and therefore enhances the immunotherapy response in different tumor types." (PMID 32630699, 2020). "Maraviroc and CCL5-neutralizing antibodies inhibited MSC-induced migration of tumor cells in vitro." (PMID 32630699, 2020). "How CCL5 production is induced in tumor tissues and whether it can be modulated therapeutically remains to be elucidated." (PMID 32973762, 2020). "Furthermore, chemokines including CCL2 and CCL5 contribute to tumor proliferation through the formation of an immunosuppressive TME by recruiting Treg cells or inflammatory monocytes and macrophages." (PMID 31991604, 2020). "CCL5 promotes tumor cell proliferation through the mTOR pathway or increases glucose uptake." (PMID 33173412, 2020). "Also, stroma-derived CCL2/CCL5 induces IL-6 release from the tumor cell generating carboplatin resistance through PYK2 pathway activation (positioned upstream of the JAK1/STAT3 pathway), a critical mediator of survival pathway activation." (PMID 32499779, 2020). "Tumor cells, by secreting CCL5, recruit normal cells and then take control of (educate) them." (PMID 32630699, 2020). "While chemokines, such as CCL5, may also recruit cells that promote tumor growth, such as Treg and macrophages, XCL1 is a specific chemoattractant for cDC1s and this chemokine could be exploited in cDC1-targeted therapies." (PMID 32486257, 2020). "Interestingly, in BC, the CCL5 secreted by lymphatic endothelial cells within the lungs and lymph nodes directs tumor dissemination into these tissues and promotes metastasis." (PMID 31991604, 2020). "In addition, PGE2 inhibits XCL1 and CCL5 secretion by NK cells, underlining the role of PGE2 as an immunosuppressive mediator to interfere with cDC1s migration to the tumor." (PMID 33679726, 2020). "The expression of CCL5 was significantly correlated with the infiltration levels of macrophages M0, macrophages M1, CD8+ T cells and T cells regulatory (Tregs) (which illustrates the relationships between the expression of CCL5 and tumor-infiltrating immune cells)." (PMID 33181717, 2020). "Finally, we investigated the connection between tumor grades and hub genes, in which LCK, CD2, CD3D, IFNG, CD8A, and CCL5 showed significant correlation with different tumor grades (p < 0.05), with grade increase corresponding to increased gene expression." (PMID 32081834, 2020). "Therefore, CCL5‐mediated tumor cell survival after drug treatment seems to be a common mechanism in cancer." (PMID 31955503, 2020). "In a study conducted by Lavergne and co-workers, the authors used a mouse model to determine whether CCL5 can control the growth of tumours." (PMID 32098198, 2020). "Blocking CCL5 alleviates the promotion of tumor progression by TADCs." (PMID 33148302, 2020). "The current research showed that CCL5 promotes tumor migration and invasion." (PMID 32963529, 2020).
tumor (continued). "Tumor-intrinsic upregulation of β-catenin signaling induces down-regulation of the chemoattractants CCL4 and CCL5 in both mice and humans, and is associated with reduced cDC1 and CD8+ T cell infiltration, increased tumor growth, and resistance to anti-PD1 therapy." (PMID 32121071, 2020). "During EBV-driven tumorigenesis, EBV replication during early lytic phase may facilitate an immune-suppressive tumor milieu (niche) via the chemotactic effect of CCL5 to attract monocytes, which further differentiate into tumor-associated macrophages (TAMs)." (PMID 33297336, 2020). "Finally, endothelial cells around the tumor secrete large amounts of the chemokine CCL5 that induces autophagy in tumor cells that display suppressed androgen receptors in a castration-resistant prostate cancer model." (PMID 33117715, 2020). "The CCL5/CCR5 axis facilitates tumor progression through multiple mechanisms." (PMID 32630699, 2020). "Similarly, CCL2 that was released by senescent melanoma cells increased tumor cell invasion and CCL5 derived from age-senescent fibroblasts elevated the proliferation of prostate epithelial cells." (PMID 32582148, 2020). "Increased benefit in terms of tumor inhibition was also obtained by measures that down-regulated CCR1 or CCL5 activities, combined with ICBs directed to PD-1 or PD-L1; here again, major roles were revealed for TAMs and MDSCs as targets whose inhibition potentiates the activities of ICBs." (PMID 32582148, 2020). "However, RANTES (CCL5) has been reported to be overexpressed in MCL tumor tissue and MCL cell lines, tentatively playing a role in recruitment of T cells." (PMID 33287742, 2020). "It has been shown that the main producer of tumor associated CCL5 is not the cancer cells, rather the local mesenchymal stem cell population." (PMID 32252260, 2020). "CCL5 is expressed not only in immune cells, but also in tumor cells." (PMID 32081834, 2020). "Besides M‐CSF, the CC chemokines CCL2, CCL3, CCL4 and CCL5 are well‐recognized chemotactic factors for macrophage populations in the tumour." (PMID 33025708, 2020). "High levels of CCL5 in cHL tumor tissues correlated with poor prognosis and monocyte infiltration." (PMID 31096713, 2019). "We next considered the possibility that CCL5 recruitment of macrophages to residual tumors may promote recurrence through macrophage-tumor cell crosstalk." (PMID 30990165, 2019). "Additionally, IFN- γ stimulated tumor cells to produce CCL5, CXCL10, and CXCL11, which further supports the notion that DCs will be attracted toward tumor." (PMID 31379812, 2019). "The secretion of CCL5, which binds to the CCR4 receptor, is strongly associated with the presence of tumor-infiltrating CD8+T cells; the upregulation of its receptor in activated vaccine-primed T cells improved tumor homing in OC." (PMID 31861351, 2019). "The residual tumor microenvironment is markedly different from that of primary tumors, with high numbers of macrophages and fibroblasts, abundant collagen deposition, and differential expression of a suite of cytokines, including CCL5." (PMID 30990165, 2019). "Deletion of CCL5 reduces tumor-infiltrating Treg cells, resulting in regression of FAK-WT tumors." (PMID 31186061, 2019). "Therefore, it is likely that the stromal cells secrete CCL5 into the tumor microenvironment and that CCL5, by binding to CCR5, activates the AKT/mTOR pathway and promotes tumor metastasis." (PMID 31500658, 2019). "It is possible that collagen deposition may promote the survival or proliferation of residual tumor cells, and that this mediates the effect of CCL5 on tumor recurrence." (PMID 30990165, 2019). "In addition, polyclonal CD4+ T cells from MHC-II-negative ovarian cancer tumor-bearing mice were able to secrete CCL5 and recruit CCR5+ DCs to the tumor." (PMID 31379821, 2019).